MEG3 (maternally expressed 3)
Synonyms: Lnc-DLK1-35; GTL2; NCRNA00023; LINC00023; onco-lncRNA-83; FP504; PRO0518; PRO2160; prebp1
Gene: Long non-coding RNA gene on chromosome 14 (100,779,206 to 100,861,031, forward strand). Ensembl gene ENSG00000214548.
Gene Ontology:
Biological process: miRNA-mediated post-transcriptional gene silencing; negative regulation of cell growth
Cellular component: RISC complex
Diseases named in the same sentence as MEG3 in open-access papers:
MEG3 is named in the same sentence as 324 diseases in open-access papers, as found by Europe PMC text mining. Sharing a sentence is not in itself a finding about the gene and the disease. The quoted sentences say what the papers report.
glioma (103 papers, 2013 to 2026). A benign or malignant brain and spinal cord tumor that arises from glial cells (astrocytes, oligodendrocytes, ependymal cells). "In line with previous evidence, administration of 5‐Aza‐2′‐deoxycytidine (5‐AzadC), a DNA methylation inhibitor, resulted in a reduction of abnormal hypermethylation of the MEG3 promoter and effectively prevented the loss of MEG3 expression in glioma cells." (PMID 40387409, 2025). "The MEG3 associated cell death mechanism of action was investigated by evaluating the cell death in U87MG glioma cells." (PMID 37525401, 2023). "The maximum MEG3 expression was observed in Grade 3 tumours indicating the contribution of IDH1 mutations since IDH1 mutant gliomas are the most frequently observed among all the grades of glioma tumours." (PMID 37525401, 2023). "MEG3 expression was compared in patient‐derived glioma cells concerning IDH1 mutation and WHO grades." (PMID 37525401, 2023). "MEG3 overexpression causes the cell cycle to stop in the G2/M phase, thus reducing the proliferation of glioma cells." (PMID 37525401, 2023). "Analysis of MEG3 expression in glioma patients showed that low expression of MEG3 was associated with poor overall survival rates, advanced WHO grade, low Karnofsky performance score (KPS), isocitrate dehydrogenase (IDH) wild-type, and tumor recurrence." (PMID 36551518, 2022). "MEG3 is a lncRNA that is significantly downregulated in gliomas and is associated with advanced tumour grade, recurrence, IDH wild-type status, and poor overall survival." (PMID 33800703, 2021). "The application of dual-luciferase reporter gene assay and gain and loss of function found that MEG3 serves in glioma cells as a competitive endogenous RNA (ceRNA)." (PMID 32420340, 2020). "Treatment of glioma cells with the DNA methylation inhibitor 5‐aza‐dC decreased aberrant promoter hypermethylation and prevented loss of MEG3 expression." (PMID 30117678, 2018). "Loss of MEG3 expression has been reported in a wide spectrum of malignancies ranging from gliomas to colon and liver cancers." (PMID 28715488, 2017). "MEG3 activity differences between different cell lines pushed us to pose this question: Are there any significant differences between patient, disease and tumour‐associated characteristics of various glioma types?" (PMID 37525401, 2023). "Several studies have implicated MEG3 lncRNA in glioma pathogenesis." (PMID 34316694, 2021). "However, loss of MEG3 expression has been observed in neuroblastomas, hepatocellular cancers and gliomas." (PMID 29348851, 2017). "MEG3 is expressed in many normal tissues, and the loss of MEG3 expression has been found in various types of human tumors, including in 25 % of neuroblastomas, 81 % of hepatocellular cancers, and 82 % of gliomas." (PMID 26253106, 2015). "Moreover, loss or significant reduction of MEG3 expression in various human primary tumors including neuroblastomas, hepatocellular cancers and gliomas has been well documented." (PMID 24098911, 2013). "Other lncRNAs, such as MEG3, have been shown to suppress glioma cell proliferation by modulating gene expression and chromatin states." (PMID 40725410, 2025). "Glioma tissues exhibit downregulated expression of MEG3 due to hypermethylation of its genomic region." (PMID 40387409, 2025). "Prior reports have established the tumor suppressor-like effects of MEG3 in cancers including glioma, gastric cancer, and melanoma." (PMID 39994235, 2025).
glioma (continued). "For example, the lncRNA MEG3, a maternally expressed gene 3, has been shown to be downregulated in glioma brain tissues compared to normal ones." (PMID 38841098, 2024). "The combined findings have provided reasonable insights into the pivotal roles played by the MEG3/miR-96-5p/MTSS1 axis in controlling the progression of glioma." (PMID 39553554, 2024). "The findings unveiled that MEG3 directly interacted with miR-96-5p, which exhibited a significant upregulation in both glioma tissues and cells." (PMID 39553554, 2024). "According to these findings, a notable decrease in MEG3 levels in glioma tissues and cells has been demonstrated." (PMID 39553554, 2024). "The anticancer effect of MEG3 also occurs in tongue squamous cell carcinoma, glioma, neuroblastoma, cervical cancer, endometrial cancer, ovarian cancer and others." (PMID 38281945, 2024). "In the MEG3 silenced glioma group, 25% of the cells were engaged in a cell death process (p = 0.0036) while only 0.5% and 2% of control and MEG3 overexpressing cells were, respectively, undergoing cell death." (PMID 37525401, 2023). "We propose that the level of MEG3 should be evaluated in the treatment of different glioma subtypes that are resistant to effective drugs to increase the potential effective drug applications." (PMID 37525401, 2023). "Previous studies showed that MEG3 overexpression would induce apoptosis in lung carcinoma and glioma cells." (PMID 37525401, 2023). "It has been reported that MEG3 gene expression levels were lower in glioma samples compared to normal and para‐carcinogenic samples taken from patients." (PMID 37525401, 2023). "Silencing of MEG3 inhibited cell proliferation and reduced cell migration while overexpression of MEG3 promoted proliferation in glioma cells." (PMID 37525401, 2023). "The level of MEG3 gene expression was significantly higher in IDH mutant glioma tumours compared to IDH wild‐type glioma (p = 0.0021)." (PMID 37525401, 2023). "In glioma cells, 5-Aza-CdR increased MEG3 expression, suppressing cell proliferation via the downregulation of the Wnt/β-catenin pathway." (PMID 36851033, 2023). "Among them, the expressions of MALAT1, LINC01018, and MEG3 were lower in glioma, and the three were discovered to be the lncRNAs that possibly targeted miR‐942‐5p." (PMID 36550594, 2023). "Patient‐derived glioma tumour samples were used to assess the effects of the MEG3 gene on the cell viability, chemosensitivity and cell migration of glioma cells." (PMID 37525401, 2023). "Silencing of the MEG3 gene significantly reduced cell migration in U87MG glioma at 48 (p < 0.001) and 72 (p = 0.010) hours of analysis and at 24 (p < 0.001), 48 (p < 0.001) and 72 (p < 0.001) hours of analysis in HUVEC cells." (PMID 37525401, 2023). "It has also been reported that in glioma cells, MEG3 reduced miR-96-5p by direct binding, leading to the suppression of cell proliferation, migration, and invasion." (PMID 36851033, 2023). "Although both cell lines originated from glioma tumours they were differently affected by MEG3 expression with respect to cell viability and 5FU response, indicating the different roles of MEG3 in different types of glioma cells." (PMID 37525401, 2023). "The precise role of MEG3 in glioma is still not well understood due to confusing results in previous studies." (PMID 37525401, 2023). "For example, LINC00312 and MEG3 have been found to act as tumor suppressors, inhibiting glioma cell proliferation and inducing apoptosis." (PMID 37444408, 2023). "The study presented here demonstrates a well‐defined characterisation of how long non‐coding RNA (lncRNA) MEG3 gene plays different roles in different types of glioma." (PMID 37525401, 2023).
glioma (continued). "High‐grade (Grade 3‐4) glioma tumours showed decreased expression of MEG3 compared to low‐grade glioma (Grade 1‐2) tumours." (PMID 37525401, 2023). "The purpose of this study is to evaluate the effect of MEG3 on glioma cells and the use of potential chemotherapeutics in glioma by modulating MEG3 expression." (PMID 37525401, 2023). "Considering the results of these previous studies, we conducted a comparative analysis of MEG3 activity in glioma and non‐cancerous HUVEC cells by suppressing and overexpressing this gene." (PMID 37525401, 2023). "MEG3 gene expression levels were analysed in patient‐derived glioma tumours including different histopathological subtypes, grades, and IDH statuses." (PMID 37525401, 2023). "Another study found that lncRNA MEG3 was downregulated in glioma and contributed to regulation of cancer cell apoptosis and proliferation (Wang, Ren & Sun, 2012)." (PMID 37810780, 2023). "The increased autophagy induced by LncRNA MEG3 improved the chemoresistance of glioma cells to cisplatin." (PMID 35674307, 2022). "Another research group clarified that the decreased expression of MEG3 was closely related to the reduction in the OS of patients with glioma." (PMID 36544907, 2022). "MEG3 has been shown to have antitumor activity in different cancer cells, such as breast, liver, glioma, colorectal, cervical, gastric, lung, ovarian, and osteosarcoma cancer cells." (PMID 35860793, 2022). "Overexpression of MEG3 significantly downregulated the expression of Bcl-xL, slightly upregulated the expression of NF-κB p65 and IκBα, and reduced the proliferation of glioma cells with increased apoptosis and the migration and invasion ability." (PMID 35860793, 2022). "Recently, a growing body of documents reported that β-Catenin is a target of MEG3 and is involved in a variety of human diseases downstream of MEG3, including Wilms’ tumor, glioma, and oral squamous cell carcinoma." (PMID 36310595, 2022). "For instance, research has confirmed that XIST is notably increased in glioma tissues, whereas MEG3 can decrease the vitality of glioma cells and promote its apoptosis." (PMID 35847925, 2022). "The availability of these gene delivery technologies, such as Ad-based gene expression technology would pave ways to overexpress or knockdown targeted genes such as maternally expressed gene 3 (MEG3) to generate a therapeutic effect in glioma." (PMID 35860793, 2022). "Our results demonstrate that lncRNA MEG3 inhibits the proliferation and growth of glioma cells in vitro and in vivo." (PMID 35860793, 2022). "Emerging evidence shows that MEG3 inhibits the proliferation, migration, and invasion of glioma cells by sponging miR-19a to upregulate the expression level of PTEN." (PMID 36544907, 2022). "It is likely that MEG3 induces apoptosis in glioma cells via downregulating the Bcl-xL gene in the PI3K/Akt/NF-κB signal pathway to reduce the development of glioma." (PMID 35860793, 2022). "Previous studies showed that compared to adjacent normal tissues, MEG3 is downregulated in a number of cancers such as breast cancer (J.J.), glioma cells, colorectal cancer, and cervical cancer (R.)." (PMID 35860793, 2022). "MEG3 has been described as a tumor suppressor in many cancer types, including glioma, hepatocellular carcinoma, and even thyroid cancer." (PMID 36231143, 2022). "Recently, several studies have shown that MEG3 inhibits glioma development through lncRNA-miRNA-mRNA networks." (PMID 36544907, 2022). "Our data from Transwell and proliferation experiments showed that overexpression of MEG3 inhibits the proliferation, migration, and invasion of glioma cells." (PMID 35860793, 2022). "MEG3 activated by vitamin D suppresses glycolysis in cancer, and MEG3 induces invasion of glioma cells via autophagy." (PMID 33425489, 2021). "This study aimed to evaluate the significance of maternally expressed gene 3 (MEG3) in the prognosis of and its immune-related roles in gliomas." (PMID 34220951, 2021).
glioma (continued). "In-vivo therapeutic applications: Targeting epigenetic regulation of MEG3 expression can provide novel therapeutic choices for glioma." (PMID 34322395, 2021). "MEG3 has shown anti-tumoral effects in several cancers, such as lung, breast, liver, gastric, colorectal, ovarian, and cervical, in addition to glioma." (PMID 34322395, 2021). "MEG3 overexpression led to cell cycle arrest in the G2/M phase in U251 cells and inhibited cell proliferation of glioma cells." (PMID 34322395, 2021). "Treatment of glioma cells with the DNA methylation inhibitor 5-AZA-2'-deoxycytidine decreased aberrant promoter hypermethylation and prevented the loss of MEG3 expression." (PMID 34316694, 2021). "We further investigated the correlation between MEG3 expression and immune cell infiltration in gliomas by using the TIMER database." (PMID 34220951, 2021). "A comprehensive analysis of 15 studies yielded a median rank = 793 and P = 6.29E-7, indicating that MEG3 was downregulated in glioma tissues." (PMID 34220951, 2021). "In the present study, we analyzed the expression level of the lncRNA MEG3 in glioma and other tumors using the Oncomine database." (PMID 34220951, 2021). "The overexpression of MEG3 in vitro suppresses proliferation and promotes apoptosis and autophagy in glioma cells." (PMID 33800703, 2021). "We also found that heterozygous deletion of MEG3 occurred more frequent than heterozygous amplification in gliomas; mRNA expression of MEG3 was significantly positively correlated with its CNV in both GBM and LGG groups." (PMID 34220951, 2021). "Several studies have shown downregulation of MEG3 in human cancers, such as breast cancer, liver cancer, gliomas, lung cancer, squamous cell carcinoma, and gastrointestinal cancer." (PMID 34220951, 2021). "Other researchers also found that MEG3 expression significantly inhibits glioma cell proliferation and promotes apoptosis and autophagy in vitro." (PMID 33558499, 2021). "Cell cycle and proliferation: MEG3 plays a substantial role in glioma proliferation and cell cycle regulation." (PMID 34322395, 2021). "The results showed that MEG3 was expressed at a lower level in most cancer types, including gliomas, than in normal tissues." (PMID 34220951, 2021). "MEG3 also modulated Wnt/β-catenin signaling, leading to enhanced tumor proliferation following MEG3 downregulation in glioma." (PMID 34322395, 2021). "To further investigate the relationship between MEG3 and level of immune cell infiltration, we assessed the correlation between MEG3 expression and immune marker genes of various immune cells in glioma using TIMER and GEPIA databases." (PMID 34220951, 2021). "The key finding of this study is that MEG3 expression is correlated with diverse immune cell infiltration levels in gliomas, particularly in LGG." (PMID 34220951, 2021). "MEG3 is downregulated in glioma cell lines, and its overexpression increased cell death and inhibited proliferation." (PMID 34316694, 2021). "We also found that heterozygous deletion of MEG3 occurred more frequent than heterozygous amplification in gliomas, and mRNA expression of MEG3 was significantly positively correlated with its CNV in both the GBM and LGG group." (PMID 34220951, 2021). "Recent studies have shown that MEG3 is overexpressed in patients with ischemic stroke and induced the apoptosis of neurons, but is downregulated in patients with glioma and Huntington's disease." (PMID 33329296, 2020). "Collectively, MEG3 can hinder cell migration and proliferation of glioma cells via modulating miR-6088/SMARCB1 axis." (PMID 32420340, 2020).